CGAS (cyclic GMP-AMP synthase)
Diseases named in the same sentence as CGAS in open-access papers (continued):
Sharing a sentence is not in itself a finding about the gene and the disease.
tumor (continued). "The cGAS-STING signal pathway was found to play an important role in the inhibition of tumor growth by paclitaxel." (PMID 34956229, 2021). "ROS/RNS also cause endogenous DNA damage that can activate the cGAS-STING pathway, which plays critical roles in natural anti-tumor or pro-tumor immunity as well as in ageing." (PMID 33670221, 2021). "Depletion of STING was then noted to decrease tissue inflammation through a diminished SASP and that tumor cells have an active pro-inflammatory phenotype dependent upon this cGAS–STING driven SASP." (PMID 34884568, 2021). "The IFN-I generated by the cGAS/STING pathway induces dendritic cell migration to the tumor and cross-priming of T cells, which are required for the antitumor effect of radiotherapy." (PMID 33561212, 2021). "First, cGAS signaling is indispensable for the establishment of an anti-tumor immune environment given that type I IFNs stimulated by cGAS signaling bridge innate and adaptive immunity." (PMID 33927185, 2021). "STING activity was partially mediated by endogenous cGAS agonists including double-stranded DNA and RNA:DNA hybrids present in the cytosol of tumor cells." (PMID 33790360, 2021). "Pathogen infection, self-DNA damage and tumor DNA are three critical factors that induce cGAS/STING signal activation." (PMID 35046953, 2021). "This response was shown to be reliant on production of Type I IFNs in dendritic cells (DC) in response to irradiated tumor cells in a cGAS–STING-dependent manner." (PMID 34884568, 2021). "To investigate the possible association between the expression of Nectin-1, HVEM, cGAS, and STING with the response to T-VEC injection in vivo, we analyzed tumor biopsies before treatment with immunohistochemical methods for the expression of these markers." (PMID 34205379, 2021). "With an 85.3% positive rate, cGAS was broadly disseminated in the nucleus and cytoplasm of tumor cells." (PMID 37305397, 2021). "Further experiments are required to link the H-1PV-modified localization (nuclear/cytoplasmic), abundance, and redox status of host HMGB1 to the deactivation of cGAS/STING in infected tumor cells." (PMID 34071585, 2021). "In primary tumor sites, the cGAS/STING pathway has an anti-tumorigenic action, being a major driver of cancer immunity, while at metastatic sites, this pathway has a pro-survival activity." (PMID 35008251, 2021). "It seems certain that the success of radiotherapy and chemotherapy in tumor therapy is closely related to the innate immune signaling partially mediated by the cGAS/STING pathway." (PMID 35265630, 2021). "In this study, the administration of recombinant IFN-β at the tumor site was shown to restore the efficacy of radiation therapy in cGas−/− and Sting−/− mice." (PMID 34571733, 2021). "Given the diversity and complexity of tumor cell immune processes, the mechanism of the cGAS-STING pathway on tumors is still a field worthy of further exploration." (PMID 34956229, 2021). "The cGAS/STING pathway can have an autocrine effect by inducing a local inflammation that supports metastatic tumor cell growth, opposite to its anti-tumorigenic action at tumor primary site." (PMID 35008251, 2021). "Mounting evidence suggests the chronic activation of cGAS/STING can paradoxically induce an immune suppressive TME that promotes tumour progression." (PMID 34885119, 2021). "The results of these studies begin to highlight the underappreciated role of tumor intrinsic STING with stromal cGAS–STING crosstalk in regulating the response to DNA-damaging therapies." (PMID 34884568, 2021). "cGAMP is produced by cGAMP synthase (cGAS) from cytosolic dsDNA and serves as a stimulator of interferon genes (STING), and this cGAS-STING pathway is of particular interest in the field of tumor immunity." (PMID 34445736, 2021). "While TLR expression was generally low in the cell lines, response to MDA5 and cGAS agonists was limited despite measurable RNA levels, as described in other tumor models." (PMID 34535668, 2021).
tumor (continued). "Activation and integrity of the cGAS-STING pathway can therefore affect the efficacy of oncolytic tumor therapy." (PMID 34205379, 2021). "Activation of the cGAS-STING pathway has been reported not only to awake the anti-tumor response of NK cells, but also to promote DCs activation and maturation, which results in the activation and infiltration of T cells to form an inflamed TME." (PMID 34625078, 2021). "It therefore requires further work to fully understand in which context cGAS-STING signaling is tumor promoting or suppressive." (PMID 33562057, 2021). "The results suggested that cGAS-STING activation regulates arginine deprivation-induced tumor growth." (PMID 34158865, 2021). "The cGAS–STING pathway can connect DNA damage to anti-tumor responses such as cell death and immune surveillance." (PMID 34858438, 2021). "The importance of the cGAS-STING pathway on the anti-tumor immune response stimulated by both RT and anti-PD1/L1 has now been established." (PMID 34681719, 2021). "Nevertheless, mounting evidence suggests that depending on the context, the cGAS/STING pathway can have tumor and metastasis-promoting functions." (PMID 34298904, 2021). "The present review article aimed to summarize the immune response mediated by cGAS and discuss its dichotomous role in tumor development and the application of STING in antitumor therapy." (PMID 35046953, 2021). "Nucleic acid substrates for cGAS in tumors can result from the release of chromatin fragments in the cytosol of tumor cells, leading to cGAS-STING activation and cell cycle arrest." (PMID 33981307, 2021). "Their products regulate the cytosolic DNA-sensing cGAS-STING innate immune pathway, activation of which is associated with improved tumor response to drug treatment and immunotherapy." (PMID 33676569, 2021). "They demonstrate radiation-induced production of cGAMP (via tumor cGAS) leads to its secretion into the extracellular space." (PMID 34884568, 2021). "2′3′-cGAMP is synthesized intracellularly by cGAS in response to double-stranded DNA, but there are several mechanisms for cell-to-cell signalling via 2′3′-cGAMP in tumours." (PMID 34905701, 2021). "The cGAS-STING thus plays a pivotal role in anti-tumor immunity and STING signaling indeed appears to be altered in a variety of cancers." (PMID 33562057, 2021). "Increased number of studies reveal the crucial role of the cGAS/STING pathway in innate antitumor immunity; however, evidence on the cGAS/STING pathway promoting tumor progression is also emerging." (PMID 35265630, 2021). "Because the primary role of cGAS/STING involves tumor clearance, the efforts were focused creating cGAS/STING agonists." (PMID 35008251, 2021). "In cancer, the intrinsic anti-tumor immune efficiency of the cGAS-STING signal pathway inspires intense efforts to boost anti-tumor immunity in next-generation cancer immunotherapies by developing cGAS-STING signal pathway agonists." (PMID 34956229, 2021). "Nevertheless, tumour cells can actively sequester the immune-stimulatory effects of cGAS-STING pathway activity away from the TME39 and processes involved in tissue remodelling can facilitate DTC invasion, dissemination and colonisation." (PMID 33731858, 2021). "The activation of the cGAS/STING pathway in response to NED is an important anti-tumorigenic mechanism via activating the immune surveillance to mediate tumor clearance." (PMID 34298904, 2021). "More importantly, exciting novel findings from this study present new evidence linking the deficiencies of DNA damage repair genes (POLQ/FANCD2) with the activation of anti-tumor immunity through the cGAS-STING-STAT1 signaling pathway." (PMID 34206946, 2021).
tumor (continued). "The role of cGAS and STING in the bystander communication between tumor and non-tumor cells is linked to the concept of cGAMP, a second messenger that activates the STING pathway." (PMID 34079557, 2021). "Promising therapeutic benefit highlights the crucial role of cGAS-STING pathway in anti-tumor immunity." (PMID 34625078, 2021). "FGA is a surrogate for chromosome instability, which has been shown to promote tumor metastasis through the activation of the cGAS-STING pathway." (PMID 34290393, 2021). "In tumor progression, some tumor cells evolve to escape the host immune surveillance gradually; for example, the cGAS or STING expression is silenced or neglected so that the signal transduction cascade is interrupted and failed to trigger immune response." (PMID 35265630, 2021). "Previous studies demonstrated that cGAS/STING pathway initiated anti-tumor immunity via activating and recruiting CD8 + T cells to the TME." (PMID 33858512, 2021). "Altogether, these observations highlights the facts that radiation-induced micronuclei and dsDNA are required for anti-tumor immunity induction via cGAS sensing and STING activation." (PMID 34079557, 2021). "Treatment of the tumor cell lysate with DNase or RNase H abrogated the binding of cGAS to dsDNA or RNA:DNA hybrids, respectively." (PMID 33790360, 2021). "If and how cGAS signaling in cancer and host cells communicate to modulate both intrinsic cellular programs and tumor microenvironment to modulate cancer growth and metastasis warrant further in-depth investigations." (PMID 33927185, 2021). "In different tumor models, activation of the cGAS-STING signal pathway was found to be significantly associated with infiltration of macrophages, CD4+ T cells, CD8+ T cells, B cells, and dendritic cells, as well as their immune markers." (PMID 34956229, 2021). "All of these indicated a prospect of tumor immunotherapy using the cGAS-STING signal pathway-related agonists alone or in combination with radiotherapy and chemotherapy." (PMID 34956229, 2021). "DNA damage induces nuclear translocation of cGAS where it inhibits homologous recombination and therefore promotes tumor growth." (PMID 34659260, 2021). "Mechanistically, the presence of cytosolic, tumor-derived DNA in immune cells is recognized by cyclic GMP-AMP synthase (cGAS) which activates stimulator of interferon (IFN) genes (STING), leading to IFN-beta production and CD8+ T cell priming." (PMID 33800547, 2021). "It has also been shown that the STING signaling pathway is activated in DCs, and cGAS is essential for the sensing by the DC of irradiated-tumor cell derived dsDNA." (PMID 34681719, 2021). "Particularly, cGAS expression by tumor cells triggers c-GAMP, which is translocated and activates STING and interferon-β production in myeloid and B cells." (PMID 34072037, 2021). "cGAS recognizes viral, bacterial, protozoal, mitochondrial, and self-DNA from the tumor or dead cells in the cytosol to activate downstream signaling pathways." (PMID 34718659, 2021). "Irradiation increases T cell receptor diversity by increasing tumor-associated antigen release and interferon secretion through the cyclic GMP-AMP synthase (cGAS)-stimulator of interferon genes (STING) pathway." (PMID 33430352, 2021). "Our results demonstrated that RRM2 silencing had anti-tumor values and activated the cGAS/STING signaling pathway." (PMID 33858512, 2021). "TREX1 and the cGAS-STING DNA-sensing pathway have also been implicated in the tumor microenvironment, where TREX1 is proposed to degrade tumor-derived DNA that would otherwise activate cGAS-STING." (PMID 33868310, 2021). "Moderate doses of radiation have also been shown to activate a type I interferon response in tumor cells through the sensing of cytoplasmic DNA derived from tumor micronuclei via the cGAS-STING pathway." (PMID 34041029, 2021).
tumor (continued). "We specifically investigated the role of different TLRs and the cGAS-STING pathway using KO mice in BCG tumor treatment using MB49 syngeneic tumor model." (PMID 34341449, 2021). "Tumor DNA carried by exosomes produced by irradiated cancer cells contributes to dendritic cell activation by stimulating IFN-I production via the cGAS/STING pathway." (PMID 33561212, 2021). "Specifically, cGAS/STING mediates increased IFN-β production in the tumor environment to promote antitumor responses upon irradiation." (PMID 33888558, 2021). "Cytosolic dsDNA and RNA:DNA hybrids partially co-localized with cGAS in all tested tumor cells.To demonstrate that cGAS physically binds to dsDNA and RNA:DNA hybrids in tumor cells, cytosolic dsDNA and RNA:DNA hybrids were immunoprecipitated in A549 cells." (PMID 33790360, 2021). "Here we show that the cytosolic DNA accumulates in tumor cells and activates the cGAS/STING pathway." (PMID 33790360, 2021). "We recently demonstrated that CIN can drive metastasis in a tumor cell-autonomous manner, through aberrant activation of the cytosolic DNA-sensing cGAS-STING pathway." (PMID 34518527, 2021). "Cytosolic DNA sensing cGAS-STING (cyclic GMP-AMP synthase – stimulator of interferon genes) pathway is emerging as an essential mechanism that drives tumor growth driven by inflammation." (PMID 34519260, 2021). "This is supported by results indicating that the knockdown of cGAS inhibits both DNA damage and tumor outgrowth in vitro and in vivo." (PMID 34906241, 2021). "This provokes tumor cell-intrinsic inflammatory signaling, mediated by aberrant activation of the cGAS-STING pathway." (PMID 34518527, 2021). "The cGAS signaling also plays important roles in regulating tumor immunity and tumor oncogenicity through modulating both tumor immune microenvironment and intrinsic tumorigenesis programs (such as cell senescence and DNA damage response)." (PMID 33927185, 2021). "We have been collecting evidence showing that LMP1 is associated with the deregulation of the cGAS-STING DNA-sensing pathway, which has potent anti-tumor activity." (PMID 34771613, 2021). "In the context of radiotherapy, similar stromal and tumor cGAS–STING signaling crosstalk is beginning to come to light." (PMID 34884568, 2021). "IFN plays an important role in tumor-specific T cell responses which means that the cGAS-STING pathway is a crucial mechanism to drive inflammation-driven tumor growth." (PMID 34858438, 2021). "RT involves the activation of an anti-tumor response through cytosolic dsDNA sensing by the cGAS-STING pathway." (PMID 34079557, 2021). "And a pan-cancer human study which analysis the association between the expression of cGAS/STING and immune cell infiltration shows that the upregulated cGAS/STING signaling is negatively correlated with the infiltration of immune cells in some tumor types." (PMID 35006429, 2020). "Although the transfer of dsDNA from tumor to immune cells is a well-recognized mechanism for the activation of cGAS-STING, recent evidence suggests that transferred cGAMP has a role to play as well." (PMID 32774773, 2020). "During Kras-driven PDAC in mice, the expression of TMEM173 or CGAS increased in a time-dependent manner in the tumor microenvironment." (PMID 33311482, 2020). "Further studies will be needed to unveil how the tumor and host-immune cGAS-STING signaling cooperates to promote tumor suppression." (PMID 32571374, 2020). "After the recognition of tumor-derived DNA within the cytosol, cGAS activates STING via the generation of 2′-5′ cyclic GMP-AMP (cGAMP)." (PMID 32526888, 2020). "This axis thus acts tumour suppressive and, indeed, several cancers display decreased cGAS-STING signalling, including colorectal carcinoma and melanoma, which has been associated with poor survival." (PMID 32873156, 2020). "The nuclear cGAS bound to the chromatin promotes tumor growth through suppressing homologous-recombination-mediated repair required for DNA repair." (PMID 33643304, 2020).
tumor (continued). "The effect of cGAS-STING on cancer is dependent on the type of tumor, host immune state, activated cell types, therapeutic intervention, and the magnitude of cGAS-STING activation." (PMID 32411126, 2020). "Several previous studies have shown that radiation therapy achieves its intended anti-tumor effects through cGAS-STING-dependent immune activation." (PMID 32774773, 2020). "Other ways that STING has been shown to be silenced in human cancer and tumor cell lines include by hypermethylation of the STING promoter and by mutations in STING or cGAS leading to loss of function or loss of protein expression." (PMID 32102850, 2020). "A recent report on the critical role of Casp9 in regulating murine tumor response to radiotherapy by regulating the cGAS/STING pathway in a cell autonomous manner provide strong evidence in this respect." (PMID 32566127, 2020). "Defective cGAS/STING signaling is closely associated with oncogenesis, immune evasion and tumor metastasis." (PMID 35006429, 2020). "Altogether, these data predict that defects in the cGAS/STING cytotoxic pathway (or TNF/IFN pathways ) should shape tumor evolution during anti-mitotic therapy." (PMID 31937780, 2020). "In the tumor microenvironment (TME), however, tumor nuclear DNA is accumulated and induces cGAS-STING signaling." (PMID 32774773, 2020). "In this review, we discuss the dichotomous roles of the cGAS-STING pathway in tumor development and the latest advances in the use of STING agonists." (PMID 32854711, 2020). "Tumor-derived DNA, such as micronuclei, DNA of dead tumor cells, cytoplasmic fragments, and free telomeric DNA, can activate the cGAS pathway and induce cellular senescence and antitumor immunity." (PMID 33142765, 2020). "Phagocytosis of extracellular tumor DNA by intra-tumoral DCs triggers the activation of the cGAS-STING pathway." (PMID 32774773, 2020). "Intratumoral recruitment of immune cells following innate immune activation is critical for anti-tumor immunity and involves cytosolic dsDNA sensing by the cGAS/STING pathway." (PMID 33013881, 2020). "On the other hand, NEAT1 was found to inhibit cGAS-STING signaling to help cells evade T cell tumor immunity." (PMID 32296457, 2020). "As an endogenous pathway for tumor-specific T cell activation, the cGAS-STING pathway is a potent therapeutic target." (PMID 32541866, 2020). "Based on the idea that cGAS-STING activation can induce a potent immune-mediated response against tumor cells, several studies have sought to explore the possibility of using STING agonists as adjuvants or chemotherapeutic agents to enhance immunotherapy." (PMID 32774773, 2020). "Another study found that microparticles yielded by tumor cells can turn macrophages into the M2 type through cGAS-STING-TBK1, contrary to previous findings." (PMID 32411126, 2020). "cGAS–STING pathway is also involved in radiation-mediated antitumor immunity via dendritic cell sensing of irradiated-tumor cells." (PMID 32382015, 2020). "Tumor-derived nucleic acids are taken up by host antigen presenting cells (APCs), translocate into cytosol, trigger the cGAS/STING pathway and contribute to the antitumor immune responses." (PMID 32000794, 2020). "As an example, TNFα, which is a recognized anti-tumor cytokine and a component of cGAS-mediated anti-tumor response, is also a central driver of RA pathogenesis." (PMID 32774773, 2020). "The activation of the cGAS-STING pathway has tremendous potential to improve anti-tumor immunity by generating type I interferons." (PMID 32887628, 2020). "cGAMP produced by constitutively active cGAS in tumor cells can trigger CD11b+ immune cells within the TME resulting in NK cell-dependent tumor rejection, and also stimulate STING-dependent type I IFN production in DCs and macrophages." (PMID 32774773, 2020). "The connection between the anti-tumor response and autoimmunity highlights the dual nature of the cGAS-STING-mediated response." (PMID 32774773, 2020).